ENSG00000199474
Synonyms: LOC124900378
Gene: Small nucleolar RNA gene on chromosome 16 (12,842,487 to 12,842,610, reverse strand). Ensembl gene ENSG00000199474.
Gene Ontology:
Biological process: RNA processing
Cellular component: nucleolus
Homologues: Paralogues in human: SNORA27 (93% identical).